CDK1 (cyclin dependent kinase 1)
Diseases named in the same sentence as CDK1 in open-access papers (continued):
Sharing a sentence is not in itself a finding about the gene and the disease.
cancer (continued). "Whether or not Cdk1/Cdk4 co-expression remained constant in cancer cells dying as a result of exposure to PRGPRP was thus examined by Western blotting." (PMID 21668989, 2011). "In our study, higher levels of CDK1 and KDF1 expression in noncancerous gastric mucosa were associated with an increased risk of future cancer development, suggesting that elevated expression of these markers may indicate a precancerous condition and play a role in gastric tumorigenesis." (PMID 39171503, 2024). "Collectively, our study demonstrates the novel mechanism of PIN1/CDK1 to cooperatively destabilize pVHL and promote tumor progression, thereby targeting PIN1 and CDK1 might be potential therapeutic strategies in the treatment of TNBC and other cancers with wild-type VHL." (PMID 36813923, 2023). "The expression of p-CDK1, p-STAT3, CD44, and Sox2 was increased by gemcitabine, while fisetin could reverse the upregulation of these proteins in the combination therapy group, suggesting that inhibition of cancer stemness-related proteins by fisetin enhanced the effects of gemcitabine." (PMID 37743465, 2023). "However, a systematic and integrative analysis of CDK1 in cancer has not been conducted." (PMID 35681641, 2022). "In this study, it was shown that EVO treatment could down-regulate the expression of cyclin B/Cdk1 complex and induce G2/M arrest in A549 cells, which was inconsistent with a previous report that EVO promoted cell cycle arrest at the G2/M phase in some cancer cell lines." (PMID 29029410, 2017). "Furthermore, cyclin D1 (CCND1), CDK1 and CDK6 mRNA levels were significantly higher in CRC compared to normal children samples, which may be related to the uncontrolled cellular proliferation in cancer." (PMID 24098334, 2013). "The results indicated that, compared to adjacent non-cancerous tissues, the H-scores of CDK1, STAT1, COL1A2, and COL1A1 in cancer tissues were significantly elevated, with statistical significance (P < 0.05)." (PMID 39911265, 2025). "This suggests that KDF1 and CDK1 may be markers independent of intestinal metaplasia severity, and could play a distinct role in MGC progression apart from the gastric precancerous cascade, potentially being more linked to cancer development rather than premalignant changes." (PMID 39171503, 2024). "Although CDKN3 has a negative adjustment effect on CDK1 and CDK2, the carcinogenic effect of CDKN3 is abnormally expressed, which is related to a variety of human cancers." (PMID 36147496, 2022). "The expression levels of EP400, HMGB2, CDK1, PPARG, and MVK were found to be significantly correlated with HMGA1 expression level in both analyzed cancer subtypes but not in non-cancerous tissue of the lung." (PMID 35805937, 2022). "Unlike silencing WEE1 in human cancer cell lines, where DDR depends on CDK2 but not CDK1, we demonstrate that DNA damage in Cdk1AF MEFs depends on CDK1 and not on CDK2." (PMID 30190546, 2019). "Further evaluation of the 12 gene expression levels in pooled TCGA RNAseq data of different cancer types revealed a strong negative correlation between CD151 and CDK1 expressions (Pearson r = −0.42, p < 0.0001)." (PMID 29843367, 2018). "The molecular and biochemical mechanisms of BA-j is the direct inhibition of CDK1 and capturing ·O2− and increasing level of H2O2 in cancer cells rather than in normal cells." (PMID 26330167, 2015). "Depletion and inhibition of the activity of CDK1, which phosphorylates BRCA1 and is necessary for the formation of BRCA1 foci and DNA damage repair by HR, was also reported to sensitize cancer but not the untransformed cells to PARP inhibition." (PMID 25026298, 2014).
cancer (continued). "In cancer models that are genetically independent of CDK2, pharmacological inhibitors suppress cell proliferation by inducing 4N cell cycle arrest and increasing the expressions of phospho-CDK1 (Y15) and cyclin B1." (PMID 39924553, 2025). "However, as you can see in the results there are two genes (i.e., CDK1 and CASP3) which are in the signatures of both pan-cancer and LGG, indicating that these two genes are important not only in LGG but also in other cancer types." (PMID 38642129, 2024). "We observed a significant correlation between the percentage of samples where a kinase is regulated in cancer and noncancer conditions (Pearson's r = 0.78, P‐value = 2.2e‐16), with AKT1 and the cell‐cycle kinases CDK1/2 and AURKB being highly regulated in both sets of conditions." (PMID 36688815, 2023). "Until now, the role of CDK1 and SPC24 coexpressions in cancer cells has not been reported." (PMID 36718148, 2023). "However, related genes (e.g., CDK1, CDK2, SMARCB1, SMARCA4) were excluded from the present study because they are either well-known genes in cancer or did not have significantly altered messenger RNA (mRNA) levels." (PMID 29712898, 2018). "The observed anti-cancer effects of PIAS2b-dsRNAi in both thyroid and non-thyroid anaplastic cells, including downregulation of PLK1, gTub, CDK1, and the presence of high-molecular weight PP2CA and PSMC5 bands, might be linked to this dysregulated proteasome activity." (PMID 38744818, 2024). "In addition, the expression of CDC25C (P = 0.000), pCDC25CSer216 (P = 0.000), CDK1 (P = 0.000), CHK1 (P = 0.000), CHK2 (P = 0.000), PLK1 (P = 0.000) and Aurora A (P = 0.008) between the primary carcinoma without metastasis and serious borderline cystadenoma were also statistically different." (PMID 32393310, 2020).
tumor (721 papers, 2001 to 2026). "In vivo, experiments showed that CDK1 restoration alleviated the tumor growth suppression caused by PSMD12 knockdown, with IHC staining of tumor tissues from nude mice further corroborating these results." (PMID 40534847, 2025). "RO-3306, a CDK1 inhibitor, reduces cell proliferation and tumor growth, induces apoptosis, causes cell stress, and inhibits cell migration." (PMID 39991589, 2025). "Elevated expression of CCNA2 and CDK1—key molecules in cell cycle regulation—is strongly associated with tumor cell proliferation." (PMID 41155558, 2025). "Failure to accurately control CDK1 activity has been linked to the loss of cell cycle control, which lies at the heart of tumor growth." (PMID 38287020, 2024). "Loss of mitosis in tumor cells is associated with a marked reduction in cyclin-dependent kinase (CDK1) transcription and/or loss of its active form (CDK1-P-Thr 161), which coincides with upregulation of CDKN1A, CDKN1B, and CDKN1C." (PMID 39766809, 2024). "Consistent with our findings concerning the impact of CAD204520 on the cell cycle, we observed a significant reduction in CDK1, which is known as a gene associated with the cell cycle and promotes tumor cell survival and resistance." (PMID 37833915, 2023). "We found CDK1 to be upregulated, which has been associated with tumor development and HCC progression." (PMID 38067357, 2023). "In this regard, it must be highlighted that both genes were upregulated in OSCC tissues where they correlated with HPV infection and that CDK1 expression was associated with tumor grade." (PMID 36768994, 2023). "In hepatic tumor cells, kaempferol stimulates autophagy via AKT and AMPK signaling molecules and initiates G2/M arrest by causing downregulation of CDK1/cyclin B in SK-HEP-1 in tumor cells of human origin." (PMID 36677655, 2023). "CDK1 controls mitochondrial metabolism for bioenergetics needed for tumor cell survival, and overexpression of CDK1 is associated with poor prognosis and metastasis in PCa." (PMID 36834602, 2023). "Many studies have demonstrated that cyclin-dependent kinase 1 (CDK1) is associated with tumor aggressiveness due to its critical role in cell cycle progression and resistance to apoptosis induction." (PMID 37189614, 2023). "CDKN1A functions as a tumor suppressor by blocking cell cycle progression via inhibiting CDK1 and CDK2, and CDKN1A-deficiency promotes spontaneous and induced tumors in different tissues." (PMID 36765862, 2023). "We found that CDK1 expression was negatively correlated with infiltration values of tumor-associated fibroblasts in COAD, BRCA-Basal, THYM, HNSC, HNSC-HPV+, LUSC, PRAD, and STAD tumors, whereas it was positively correlated in KICH, KIRC, KIRP, MESO, and TGCT." (PMID 36090896, 2022). "Dysregulation of CDK1 was confirmed to cause cell cycle disturbance, which then leads to tumor production." (PMID 35251377, 2022). "The data revealed that CDK1 expression levels showed a strong association with the stage of tumor in lung cancer patients as well as HSP90AA1 also showed a strong association with the stage of tumor in lung cancer patients." (PMID 35330393, 2022). "It has been clarified that cell-cycle dysregulation is a central hallmark of tumor progression, in which CDK1 is one of the primary master regulators involved in the entry of the cell into the M phase." (PMID 36160115, 2022). "Cell proliferation–related genes, including Mki67, Cdk1, Plk1, and Ccnb1, were downregulated in tumor-infiltrating SENP7-deficient CD8+ T cells." (PMID 35143421, 2022). "We used TIDE, XCELL, MCPCOUNTER, and EPIC algorithms to investigate the relationship between the level of tumor-associated fibroblast infiltration and CDK1 gene expression in different types of TCGA tumors." (PMID 36090896, 2022).
tumor (continued). "CDK1 genes are significantly overexpressed in tumor cells of PDAC patients, which is associated with more advanced stages of PDAC and is an indicator of poor survival rates for patients." (PMID 34503199, 2021). "They found in in vivo experiments that the tumor volume increased significantly in overexpressed wild‐type CDK1 cells compared with vector control or kinase‐dead variant CDK1 cells." (PMID 34586751, 2021). "We focused on CDK1/CDK4/CDK6 given that increased expression of CDKs has been associated with many tumor types, and oral, highly selective CDKs inhibitor have already been developed." (PMID 32811807, 2020). "Using a siRNA knockdown approach in combination with metformin treatment, we found that loss of CDK1/CDK4/CDK6 in combination with metformin exhibited enhanced antitumor properties in several tumor cell lines." (PMID 32811807, 2020). "Dinaciclib caused inhibition of cell proliferation and tumor growth, possibly attributable to its suppression effects on both CDK1 activity and expression as observed in A549 cells in this study and previously by others as well." (PMID 32375399, 2020). "Adding VPA to the cell cultures induced a loss of cdk1 and cyclin B in both sensitive and resistant tumor cells." (PMID 31010254, 2019). "p27 (also known as KIP1, encoded by CDKN1B) is an atypical tumor suppressor that regulates G0 to S phase transition by binding to and regulating the activity of CDK1 and CDK2." (PMID 30450190, 2018). "The expression levels of the core genes RAD21, HDAC2, and CDK1 were increased in HCC tissues compared with adjacent non-tumor tissue, and their expression levels were associated with the OS of HCC patients." (PMID 28434945, 2017). "As well as providing a potential route to targeting MYC driven tumours, CDK1 inhibition has also been proposed as a route to causing chemosensitivity, enhancing the effects of PARP inhibitors as well as PI3-kinase inhibitors." (PMID 26881434, 2016). "Genotoxic-induced CHK1 activity (pS296 CHK1) and cell cycle arrest (pY15 CDK1) were inhibited both in vitro and in human tumor xenografts by CCT245737, causing increased DNA damage and apoptosis." (PMID 26295308, 2016). "Although CDK1 was highly expressed in tumor tissues, its loss from the cytoplasm unexpectedly predicted poor survival and conferred resistance to chemotherapy in multiple cell lines, especially microtubule-directed agents." (PMID 21887332, 2011). "Our findings may help understand the biological processes underlying tumor development and progression and suggest CDK1 and KIF11 as possible key molecules in the development of CRC." (PMID 40457491, 2025). "The observed positive correlation with TMB further indicates that CDK1 may be associated with genomic instability, a feature often linked to tumor aggressiveness and immunogenicity." (PMID 41278293, 2025). "In the field of immunotherapy, CDK1 expression is closely associated with immune cell infiltration patterns in the tumor microenvironment, and this finding provides a rationale for the development of novel therapeutic strategies based on immune checkpoint inhibitors." (PMID 40332418, 2025).
tumor (continued). "This means that CDK1 may have more active expression in tumors with high mutation load, suggesting that it may be associated with increased tumor mutation levels." (PMID 41278293, 2025). "By contrast, luminal cluster 2 was enriched in a proliferative gene signature (Mki67, Ccnb2, Cdk1, Ccnb1 and Ccnd1), which may be associated with cycling progenitors fuelling tumour growth." (PMID 38238426, 2024). "Moreover, the overexpression of CDK1/2 interferes with DNA repair pathways, causing genomic instability and tumor growth progression." (PMID 38606093, 2024). "CDK1 is also associated with tumor mutational burden (TMB) and microsatellite instability." (PMID 39445019, 2024). "To summarize, we found that ASPM, CCNB2, and CDK1 expressions were significantly associated with tumor purity, which could be a sign that ASPM, CCNB2, and CDK1 played specific roles in immune infiltration in ACC." (PMID 35693556, 2022). "According to in vitro experiments of human ACC cell line, SW13 cells, overexpression of ESM1 upregulated CDK1 and p21-mediated G2/M-phase transition, cell proliferation, cell migration, cell invasion, and accumulation of tumor mutation burden (TMB) via DLL4-Notch signaling pathway." (PMID 34858850, 2021). "Therefore, we investigated the mechanism of CDK1 overexpression in leukemogenesis and the anti-tumor efficacy of CDK1 inhibitors in DNMT3A mutation-related AML." (PMID 34067359, 2021). "Moreover, overexpression of BUB1B, CCNA2, CDC20, and CDK1 in tumor tissues was significantly associated with disease-free survival (DFS) in PDAC patients (Log rank P=0.00565, P=0.0357, P=0.00104, and P=0.00121, respectively)." (PMID 30765611, 2019). "In addition, reconstitution of p21 in tumor cells with high levels of brachyury is shown here to increase the stability of the CDK1 protein, leading to higher levels of CDK1 expression and the anticipated increase in tumor susceptibility to lysis." (PMID 29774202, 2018). "However, we do note that we also observed the KRAS selective effect of CDK1 inhibition in tumour cell lines with naturally occurring KRAS mutations." (PMID 26881434, 2016). "Furthermore, cyclin-dependent kinase 1 (CDK1), a serine/threonine kinase, is responsible for the phosphorylation of hTERT which is substantial for hTERT-mediated RdRp activity and has been reported to be associated with tumor aggressiveness." (PMID 38246945, 2024). "However, among all genes associated with LUAD prognosis, only CDK1 was differentially expressed in tumor and normal lung tissues, indicating that CDK1 might be a valuable biomarker for prognostic prediction and targeted therapy in LUAD." (PMID 36950551, 2023). "Hypomethylation status of CDK1 in some tumors may lead to activation of other oncogenes, while hypermethylation status in other tumors may further exacerbate carcinogenesis by silencing tumor-associated suppressor genes." (PMID 36090896, 2022). "Therefore, determining whether MMB–FOXM1-driven transcription can be targeted following the loss of CDK1 inhibitory phosphorylation may expand the range of tumours that could benefit from PKMYT1 inhibitors." (PMID 35444283, 2022). "Whether the CDK1 gene and tumor-associated fibroblasts have competitive inhibitory or synergistic effects on promoting tumor cell proliferation and the progression of malignancy in these tumors is unclear, and the mechanism of action between the two needs a detailed investigation." (PMID 36090896, 2022). "Our findings elucidate that CDK1 expression increases in more than 20 human tumors and is highly correlated with oncogenic signature gene sets, biological pathways, immune cell infiltration, tumor mutational burden, microsatellite instability, and lower survival rate across multiple tumors." (PMID 35681641, 2022).